IL6 (interleukin 6)
Diseases named in the same sentence as IL6 in open-access papers (continued):
Sharing a sentence is not in itself a finding about the gene and the disease.
breast cancer (continued). "IL-6, TGF-beta, TNF-alpha, NF-kB, COX-2 and PGE-2 are pro-inflammatory cytokines present in the TME of ER+ breast cancer that are capable to activate pro-tumoral pathways mediating proliferation, immune evasion and metastasis." (PMID 38332913, 2023). "Although ΙL-1B is primarily produced from immune cells, it can be synthesized and secreted from several types of solid tumors, where it stimulates the expression of IL-6 and COX-2, which are promoting factor for breast cancer aggressiveness." (PMID 38283944, 2023). "Breast cancer cells induce the expression of cytokines (CCL2, CCL5, IL-1β, and IL-6) and immunomodulators (COX2, HIF-1α, VEGFα, and PD-L1) by cancer-associated adipocytes." (PMID 36670988, 2023). "IL-6 produced by CAFs stimulates the signal transducer and activator of transcription 3 (STAT3) pathway, promoting breast cancer cell growth and radioresistance." (PMID 37496657, 2023). "In cancer cell lines, manuka honey inhibited IL-6 release by AGS (human gastric adenocarcinoma) cells, whereas thyme honey inhibited IL-6 secretion and TNF-β activity by PC-3 (human prostate cancer) cells and IL-6 in human breast cancer cell lines." (PMID 38045104, 2023). "Significantly reduces the IL-6, IL-1, TNF- levels, protein, and nucleic acid content of breast cancer cells MCF-7." (PMID 36742434, 2023). "IL-6 secretion is tightly regulated by autophagy, and the autophagy activity in breast cancer cells and tumor microenvironment cells regulates EMT mediated by the IL-6/STAT and IL-6/MAPK pathways." (PMID 36831154, 2023). "A review by Yu et al26 demonstrated that cytokines such as IL‐1Ra, IL‐6, and TNF‐α increase the permeability and dysfunction of the blood–brain barrier (BBB) and promote the occurrence of depression in breast cancer patients." (PMID 36965094, 2023). "In breast cancer cells, TLR4 activation promotes the migration of these cells and induces the production of inflammatory cytokines and oncogenes such as IL-6 and VEGF." (PMID 37371732, 2023). "IHC was carried out to analyze the levels of IL-6 and p-STAT3 in a cohort of 103 patients with breast cancer." (PMID 36635302, 2023). "A-FABP, which is highly expressed in TAMs of mouse and human breast cancer cells, enhances IL-6/STAT3 signaling by regulating the NF-κB/miR-29b pathway, thereby promoting breast cancer growth and metastasis." (PMID 37781517, 2023). "It played a critical role in different stages of cancer progression and was essential for transduction of IL6-class inflammatory cytokine signaling; it was also involved in mediation of the oncogenic activation of STAT3 in mammary cancer cells." (PMID 37895906, 2023). "Lin28B reduced the expression of let-7s in breast cancer exosomes and regulated the expression of CXCL, IL-6, and IL-10 in neutrophils, resulting in immunosuppressive PMN, thus promoting lung metastasis of breast cancer." (PMID 37046819, 2023). "Further evidence found that the cGAS-STING pathway induces inflammatory response through IL-6, IL-6R and STAT3, and induces CD8+T cell infiltration to enhance anti-tumor immune responses in breast cancer." (PMID 37051596, 2023). "miR-214 expression correlates with IL-6 and STAT3 signatures in TCGA breast cancer and melanoma datasets." (PMID 36639824, 2023). "In this study, we showed that CAF-derived IL-6 induced STAT3 activation, which promoted breast cancer cell growth and radioresistance." (PMID 36635302, 2023). "Targeting IL-6 or progranulin or both through sortilin could potentially be a new treatment approach for breast cancer patients with elevated progranulin and/or IL-6 levels, further emphasizing sortilin as an important therapeutic target for treating breast cancer." (PMID 38136303, 2023). "IL-6 and p-STAT3 levels correlated with a poor radiotherapy response in patients with breast cancer." (PMID 36635302, 2023).
breast cancer (continued). "It appears that IL6-adenosine loops between CD73+ gamma delta Tregs and CAFs play a critical part in promoting tumor progression and immunosuppression in breast cancer." (PMID 37496657, 2023). "The results of Meng’s meta-analysis showed a significant reduction in IL-2, IFN-γ, IL-6, IL-1β, and TNF-α levels in breast cancer patients participating in the Qigong practice group." (PMID 36831519, 2023). "Several interleukins including IL-1, IL-6, IL-11, IL-19, and transforming-growth factor β (TGF-β) promoted breast cancer cell proliferation and/or invasion." (PMID 37340387, 2023). "Here we show that an increased production of key cytokines (IL‐6, IL‐8, MCP‐1 and CXCL1), known to facilitate transmigration of breast cancer cells across the BBB, were increased following NHA exposure to MBM‐EVs or miR‐146a‐5p mimic." (PMID 37759347, 2023). "Analysis of genes relating to cytokine release by endothelial cells showed that the top 3 upregulated cytokines in the T group were IL-6, RELLE and PLXAN2, suggesting that breast cancer promoted an inflammatory state among endothelial subpopulations." (PMID 37153595, 2023). "One recent study demonstrates that narasin inhibits tumor metastasis and growth of ERα-positive breast cancer cells, and this is through inactivation of the TGF-β/SMAD3 and IL-6/STAT3 signaling pathways." (PMID 37864240, 2023). "To summarize, CAF-secreted IL-6 activates STAT3 signaling, which promotes breast cancer cell growth and radioresistance." (PMID 36635302, 2023). "We used MC38 colorectal cancer cells and 4T1 breast cancer cells, which are sensitive to PD-L1 monotherapy and express PDL-1 and IL-6." (PMID 37924094, 2023). "Considering breast cancer alone, a study analyzing the role of IL6/IL8 ratio on cell proliferation, researchers showed having an IL6/IL8 ratio larger than 2.0 will induced cellular growth in a transformed cell line." (PMID 37181043, 2023). "Some cytokines (leptin, IL-1β, IL-6, IL-8, IL-23, IL-17, TGF-β, IL-10) are mostly reported to stimulate while others (Il-2, IL-12, IFNs) inhibit breast cancer proliferation and/or invasion." (PMID 36835413, 2023). "In another study, it was shown that inhibition of autophagy by knockdown of ATG7 or BECN1 modified the CD44+/CD24low/- (stem cell phenotype) population of breast cancer cells by regulating CD24 and IL-6 secretion." (PMID 37886168, 2023). "Since breast cancer cells mediate their paracrine pro-carcinogenic effects through the IL-6/STAT3 pathway, we tested the effect of exogenous recombinant human IL-6 (rIL-6)." (PMID 36359766, 2022). "Cytokines such as IL-6 and tumor necrosis factor-alpha (TNF-α) released by breast cancer cells can stimulate the expression of KDM2A in fibroblasts." (PMID 36291773, 2022). "Breast Cancer: curcumin down regulate of NF-jB, AP-1, COX-1, and –2, VEGF, fibroblast growth factor (FGF), cyclin E, IL-6, and –11, TGF-b, MMP-2, MMP-9, and MMP-13, the upregulation of tissue inhibitor of metalloproteinase-1." (PMID 36712505, 2022). "In line with breast cancer stem cells, knockdown of ATG7 in immortalized pancreatic stellate cells reduces not only IL-6 secretion but also the release of ECM proteins such as type I collagen and fibronectin." (PMID 35927755, 2022). "IL-6, like MCP-1, is produced by mesenchymal stem cells, promoting the migration and metastasis of breast cancer cells, which can serve as one of the factors of tumor growth and progression." (PMID 36286034, 2022). "Augmentation of the IL-6-meditaed inflammatory loop induces resistance to trastuzumab, a HER2-targeted therapy used for HER2-positive breast cancer, by expanding the CSC population." (PMID 36010693, 2022). "For example, IL-6 enhances both stimulatory and inhibitory roles of MDSCs via STAT3 signaling pathways in breast cancer." (PMID 35359390, 2022). "IL-6 secreted by adipocytes triggers IL-6/STAT3 axis and drives the acquisition of EMT properties in breast cancer cells." (PMID 36077676, 2022).
breast cancer (continued). "In cases with breast cancer, we previously demonstrated that osteopontin and heparin-binding epidermal growth factor-like growth factor (HB-EGF), in addition to IL-6, were involved in cancer cell growth." (PMID 35835809, 2022). "Breast cancer associated fibroblasts (bCAFs) are dependent upon MCL-1 for survival and through secretion of IL-6, bCAFs can induce upregulation of MCL1 mRNA and protein in luminal breast cancer cells to reduce sensitivity to BCL-2/XL inhibition." (PMID 35349392, 2022). "Taken together, strategy targeting the IL-6/JAK/STAT3 signaling pathway, which has already been shown to be beneficial in certain cancers including breast cancer, has proven to be effective." (PMID 35924148, 2022). "It was reported that the activation of IL-6/JAK2/STAT3 pathway promotes proliferation, invasion, metastasis and angiogenesis, and inhibits apoptosis in breast cancers." (PMID 36431925, 2022). "However, in the present work, IL-6 associations with breast cancer risk did not vary by tumor size." (PMID 35948877, 2022). "Thus, IL-6 by itself, and synergistically with acidic fibroblast growth factor (aFGF), could dramatically alter the social behavior of breast cancer cells to enhance cell motility and cancer-cell dispersal in a direction conducive to increased local invasiveness as well as distant metastasis." (PMID 35406728, 2022). "Within 4-8 weeks after surgical resection, the breast cancer patients with depressive symptoms showed greater serum TNF-α, IL-1β, and IL-6 levels." (PMID 36275706, 2022). "Taken together, mammary tumor progression is enhanced by this macrophage subset, which is mechanistically accumulated in the tumor stroma through FABP4 mediated miR-29b/IL-6/STAT3 cascade." (PMID 36060264, 2022). "IL-6 secreted from differentiated cancer cells supports CSC survival, metastasis, and treatment resistance in breast cancer." (PMID 35743249, 2022). "In breast cancer, TEVs carrying PGE2 and TGF-β switched the differentiation of IMCs into MDSC and also stimulated MDSC expression of Cox2, IL-6, VEGF, and arginase-1." (PMID 36612080, 2022). "The breast cancer MDA-MB-231 cell line elicits the production of proinflammatory cytokines TNF-α, IL-1beta, IL-6, IL-8, and IL-10." (PMID 36501201, 2022). "We substantiated these findings, as the SASP, which is enriched in IL6, also induced NED in LNCaP cells, arguing in favor of using IL6 to induce NED in breast cancer cells." (PMID 35653631, 2022). "Previous study showed that IL-6 acts as an inducer of an EMT phenotype in breast cancer cells, which implicates its potential to promote breast cancer metastasis." (PMID 35303925, 2022). "Thus, IL-6 and G-CSF may work in concert on neutrophil function to promote breast cancer growth." (PMID 35226704, 2022). "IL-6R is involved in the IL-6/IL-6R/STAT3 signaling pathway, whose role in breast cancer progression has been extensively demonstrated." (PMID 35406622, 2022). "EPNE significantly downregulated the level of inflammatory markers such as TNF-α, and IL-6 as compared to groups of the combination of ER + PTX, ER, and PTX alone in DMBA induced breast cancer group." (PMID 36330087, 2022). "We further demonstrate the role of TAMs derived IL-6 in enrichment of CSCs and tumor progression through STAT-3 pathway in breast cancer using both in vitro and in vivo models." (PMID 35300689, 2022). "Performing a cytokine antibody array on a multidrug-resistant breast cancer cell line, MCF-7/R, it was observed that IL6 and IL8 exhibited a significantly increased level of these cytokines, suggesting their implication in drug resistance." (PMID 36114508, 2022). "The IL-6 signal transduction pathway including IL-6, IL-6R, sIL-6R, gp130, JAK, and STAT3 has been suggested as promising therapeutic targets for breast cancer." (PMID 35924148, 2022).
breast cancer (continued). "In this review, we summarize the role of the IL-6 cytokine family—specifically IL-6 itself, LIF, OSM, and IL-11—as relevant players during breast cancer progression." (PMID 35163731, 2022). "Inhibiting IL-6 and VEGF increased functional vascular density, reduced hypoxia, attenuated infiltration of Tregs, decreased mammary tumor growth, and metastasis." (PMID 35186923, 2022). "In contrast, the study found that 4T1 breast cancer cells can promote the expression of Fra-1 in RAW264.7 in response to LPS and increase IL-6 production." (PMID 36032067, 2022). "OSM can also further activate IL-6/JAK/STAT3 signaling both in vitro and in vivo to promote breast cancer progression." (PMID 35371975, 2022). "In turn, STAT3 increases TIMP-1 secretion by breast cancer cells, leading to a TIMP-1/CD63/integrin β1/STAT3 positive feedback loop, which can be further fueled by IL-6." (PMID 36291767, 2022). "For example, conditioned medium from IL-6-positive breast cancer cells stimulated STAT3 phosphorylation in IL-6-negative breast cancer and non-cancerous epithelial cells, while administration of anti-IL-6 antibodies abrogated these effects." (PMID 35371975, 2022). "In the breast cancer surgery group, postoperative VEGF levels were statistically significantly lower compared to preoperative levels (P < 0.05); postoperative IL-6 levels were statistically significantly higher compared to preoperative levels (P < 0.05)." (PMID 36531035, 2022). "We demonstrated that core fucosylation of IL6ST promoted IL-6– and OSM-stimulated cellular signaling important for breast cancer EMT and metastasis." (PMID 35303925, 2022). "Papila and colleagues compared serum values of NF-ƙB, PTX-3, IL-6, CRP, TNF-α, and sTRAIL (soluble TNF-related apoptosis-inducing ligand) and PCT (procalcitonin) in 40 individuals diagnosed with breast cancer, 40 with colon cancer, and 30 health controls." (PMID 36499628, 2022). "ROC analysis of serum IL-6, IL-17 and VEGF in differentiating breast cancer from benign control group." (PMID 36531035, 2022). "Previous evidence also revealed IL-6 promotes TNBC cell survival, increases breast cancer stemness, and contributes to chemoresistance of MDA-MB 231 cells." (PMID 35960749, 2022). "While in dendritic cells of mice with breast cancer, HCAR1 activation is also shown to reduce the production of IL-6 and IL-12." (PMID 36615018, 2022). "We identify an IL-6-dependent positive feedback axis to facilitate nuclear METTL3 functions, eliciting breast cancer metastasis." (PMID 36289222, 2022). "Our previous work with breast cancer patients demonstrated that high levels of TGF-β, TNF-α, VEGF, IL-6, IL-8, and IL-10 correlated with poor prognosis, while IL-21 and CCL-2 are related to a better outcome." (PMID 36428939, 2022). "In these cancer cell lines, autophagy led to paracrine secretion of IL-6, a pro-inflammatory cytokine, leading to increased signal transducer and activator of transcription (STAT3) phosphorylation and breast cancer stem-cell proliferation." (PMID 36295867, 2022). "In breast cancer, tumor cells co-cultured with CAF showed increased expression of IL-6 and IL-8, leading to more invasive and angiogenic capacity." (PMID 35743249, 2022). "Nevertheless, here we have proved by various methods that breast cancer cells can activate macrophages into TAMs and these TAM derived IL-6 induces CSC enrichment and tumor progression in breast cancer." (PMID 35300689, 2022). "The emerging role of IL-6/JAK/STAT3 in promoting the breast CSC subpopulation and breast cancer metastases in vivo underscores the therapeutic potential in exploiting the IL-6/JAK/STAT3 signaling axis in metastatic breast cancer." (PMID 35371975, 2022). "In breast cancer, ZEB1 promotes inflammation in the tumor microenvironment by regulating the secretion of the proinflammatory cytokines interleukin 6 (IL-6) and IL-8 and subsequently inducing the growth of fibroblasts and myeloid-derived suppressor cells." (PMID 35454770, 2022).
breast cancer (continued). "A novel in-house prepared IL-6 pathway inhibitor namely 6a, which is capable of selectively inhibiting STAT3 activation following IL-6 stimulation in MDA-MB-231 breast cancer." (PMID 35924148, 2022). "In breast cancer, NIC reverses the adipocyte-induced epithelial–mesenchymal transition (EMT) in breast cancer cells by inhibiting the interleukin-6/STAT3 signaling axis, thus inhibiting cell migration and invasion ability." (PMID 36555754, 2022). "A recent study demonstrated that Chinese propolis (25, 50 & 100 μg/ml) treatment inhibits cell proliferation by targeting glycolysis enzymes and proinflammatory cytokines including TNF-α, IL-6, and NLRP3 in the breast cancer cells." (PMID 35754701, 2022). "In breast cancer, CD10+GPR77+ CAFs are found to sustain cancer stemness through secreting IL-6 and IL-8, thus mediating tumorigenesis and therapy resistance." (PMID 36319622, 2022). "IL-6 and phosphorylated-STAT3 (phospho-STAT3, pSTAT3) are co-overexpressed in primary breast cancer specimens." (PMID 35371975, 2022). "In the stromal microenvironment, SASPs, such as IL-6, IL-8, and MMP-1, can stimulate the proliferation and metastasis of breast cancer cells." (PMID 36291773, 2022). "Thereby, regulation of IL-8 and IL-6 by LPA mainly in ovarian cancer, but also in some breast cancer cell lines was described." (PMID 35365723, 2022). "IL-6 and IL-8 secreted from adjacent cells in the TME such as TAMs activate the STAT3 signaling pathway in breast cancer cells." (PMID 35847899, 2022). "We first looked at IL6 and IL13Rα2, which have previously been reported to be regulated by INHBA in ovarian and breast cancers." (PMID 35248133, 2022). "The IL-6 signaling loop mediated drug resistance to PI3K inhibitors via inducing epithelial-mesenchymal transition (EMT) and CSCs expansion in human breast cancer cells." (PMID 35924148, 2022). "Alternatively, long-term DEHP exposure can also induce upregulation of the inflammatory cytokines IL1α, IL1β, IL6, and GM-CSF through the MAPK/p38 signaling pathway to facilitate breast cancer progression." (PMID 35203627, 2022). "Our previous data indicate that IL-6 facilitates LH2 expression in breast cancer, and a high expression of LH2 in breast cancer leads to epithelial–mesenchymal transition (EMT) and poor prognosis." (PMID 35559258, 2022). "Comparison of serum IL-5, IL-6, IL-8, IL-17 and VEGF levels in the breast cancer surgery group before and after surgery." (PMID 36531035, 2022). "Our results depict that activated macrophages derived IL-6 regulates CSC enrichment, tumor growth, metastasis and angiogenesis in breast cancer through STAT-3 pathway." (PMID 35300689, 2022). "The up-regulated IL-6 and FGF-2 abrogated or inhibited the anti-VEGF therapy in obese breast cancer patients and mouse model." (PMID 35701840, 2022). "In turn, IL-6/STAT3 signaling promotes EMT by regulating estrogen receptor α (ERα), which is essential for breast cancer metastasis." (PMID 35743249, 2022). "Mechanistically, IL-6 is implicated in both MDSC recruitment and Th17/ Th22 polarization, yet no studies have explored whether chronic overexpression of IL-6 from a developing tumor may, in fact, elicit both MDSC and type 3 Th expansion in the context of mammary carcinoma." (PMID 36142210, 2022). "In mammary tumor cells, radiation stimulated EMT through the IL-6/JAK/STAT3 signaling axis, which upregulated JAG1, DLL4, and Notch2 transcripts, and GSI addition effectively attenuated migration and mesenchymal markers expression in the irradiated cells." (PMID 34680255, 2021).